MMP9 (matrix metallopeptidase 9)
Diseases named in the same sentence as MMP9 in open-access papers (continued):
Sharing a sentence is not in itself a finding about the gene and the disease.
schizophrenia (continued). "Increased levels of MMP-9 have been demonstrated in human subjects with FXS, ASD, bi-polar disorder and treatment-resistant schizophrenia." (PMID 26283917, 2015). "Similar to schizophrenia, there are no studies measuring MMP9 blood levels in patients with bipolar disorder." (PMID 20037727, 2009). "Based on it being an MMP-9 inhibitor and microglial activation blocker, the tetracycline antibiotic minocycline has been proposed for the treatment of depressive symptoms as well as negative symptoms in schizophrenia." (PMID 35370878, 2022). "Apart from MMP9, hypomethylations have also been detected in other genes, such as AluY A3 CpG, promoter of GRIN2B, CpG2 and CpG3 in TREM2 intron 1, CpG sites in FAM63B and intergenic region on chromosome 16, CpG sites in TBC1D22A, and COMT in schizophrenia compared with controls." (PMID 34366776, 2021). "In another study on peripheral blood mononuclear cells (PBMC), it has been revealed that deficit schizophrenia patients presented lower DNA methylation in MMP9 compared with non-deficit schizophrenia patients, and MMP9 expression is positively correlated with negative symptoms in schizophrenia." (PMID 34366776, 2021). "Similarly, MMP-9 gene expression in blood mononuclear cells was found to be upregulated in schizophrenia patients who did not undergo treatment." (PMID 31172215, 2019). "Stress further decreased MMP-9 levels in heterozygous mice, which may be directly related to the endophenotype of negative symptoms of schizophrenia." (PMID 31555105, 2019). "In addition, MMP9 is involved in the degradation of the perineuronal net, a type of ECM that wraps fast-spiking parvalbumin interneurons; the perineuronal net is known to be affected in the medial prefrontal brain of schizophrenia patients." (PMID 29875399, 2018). "According to exposing the MMP9 heterozygous mice to psychosis-related locomotor hyperactivity induced by an NMDA receptor antagonist, they also indicated the lower MMP9 level influenced performance in a behavioral model of the positive symptoms of schizophrenia." (PMID 30619470, 2018). "However, the correlation between MMP-9 upregulation, lipid peroxidation, and BBB breakdown in schizophrenia remains speculative." (PMID 28588507, 2017). "Studies on the MMP9 levels in schizophrenia have not yet been performed." (PMID 20037727, 2009). "Thus, we investigated whether the negative-like schizophrenia symptoms that were observed in stressed Mmp-9 heterozygous mice could be treated with an antipsychotic." (PMID 31555105, 2019). "The influence of antipsychotic medication on MMP9 expression and methylation does not here differentiate typical and atypical antipsychotics, although differential epigenetic modification of various antipsychotics in the patients with schizophrenia has been reported." (PMID 30619470, 2018). "MMP-9 also acts via non-synaptic mechanisms that may be relevant to schizophrenia pathology." (PMID 28588507, 2017). "A positive correlation was found between gene expression of MMP9 and negative symptoms after controlling for age and CPZ-equivalents in the total schizophrenia group, suggesting the increased MMP9 might have a potential effect on negative symptoms." (PMID 30619470, 2018).
abdominal aortic aneurysm (56 papers, 2004 to 2025). Enlargement and ballooning of the vessel that supplies arterial blood to the abdomen, pelvis and legs. "In the vascular biology, a 2024 Mendelian-randomization analysis has implicated MMP-9 expression as causally linked to thoracic and abdominal aortic aneurysm risk, thereby linking proteolytic imbalance to structural vascular failure." (PMID 41304763, 2025). "Single nucleotide polymorphisms (SNPs) of MMP-9 have also been positively associated with both slow-growing and aggressively evolving abdominal aortic aneurysms." (PMID 35563383, 2022). "On the other hand, recent study showed that MMP-9 deficiency augmented angiotensin II-induced abdominal aortic aneurysms, related to impair collagen organization and angiogenesis, smooth muscle cell migration and geometrical arterial remodeling." (PMID 32321550, 2020). "The increased expression of MMP9, predominantly in macrophages has also been implicated in acute vascular crises such as atherosclerotic plaque rupture, abdominal aortic aneurysm, and aortic dissection." (PMID 29255427, 2017). "MMP-3, as well as MMP-9, has been implicated in the pathogenesis and treatment of abdominal aortic aneurysms." (PMID 19886986, 2009). "FOSB expression in vascular smooth muscle cells (VSMCs) influences their phenotypic transformation, promoting MMP2/MMP9 expression, potentially accelerating abdominal aortic aneurysm (AAA) development." (PMID 40486911, 2025). "Statin therapy has also demonstrated efficacy in decreasing MMP-3 and MMP-9 levels in patients with abdominal aortic aneurysms, as well as MMP-2 and MMP-9 levels in individuals with arterial aneurysmal disease." (PMID 39200884, 2024). "Treatment with senolytic agents dasatinib and quercetin already showed effectivity against abdominal aortic aneurysm growth in aged mice infused with angiotensin II, where reduced expression of Mmp2 and Mmp9 was observed upon treatment." (PMID 38902222, 2024). "Increased proteolytic activity of MMP-2 and MMP-9 and consequent high circulating values of these MMPs have also been found in connection to abdominal aortic aneurysm rupture." (PMID 39408865, 2024). "High expression of soluble MMP-9 can be measured in the plasma of patients with abdominal aortic aneurysm or aortic dissection." (PMID 36684579, 2022). "In particular, a study that analyzed infrarenal aortic specimens proved that MMP-9 mRNA expression is higher in moderate diameter abdominal aortic aneurysms (5–6.9 cm) than in small ones, as they present better chances of further expansion." (PMID 35563383, 2022). "For example, the plasminogen/MMP-9 cascade is a promising target for regulating inflammatory responses and development of abdominal aortic aneurysms (AAAs)." (PMID 34769032, 2021). "Elevated plasma concentrations of MMP-3 and MMP-9 have been demonstrated in patients with abdominal aortic aneurysms." (PMID 34572455, 2021). "In animal models, female sex hormones reduced MMP-2 and MMP-9 activity in aortic tissue and protected from experimental abdominal aortic aneurysm formation." (PMID 34526107, 2021). "Nevertheless, previous studies have observed higher MMP-9 activity in females, compared to males, in various vascular pathologies including advanced coronary atherosclerotic plaques and abdominal aortic aneurysm." (PMID 34526107, 2021). "Toll-like receptor 4 (TLR4) and matrix metalloproteinase 9 (MMP9) have been investigated to play significant roles in the formation of abdominal aortic aneurysm (AAA)." (PMID 34348653, 2021). "RAGE also promotes the development of abdominal aortic aneurysms by inducing matrix metalloproteinase 9 (MMP9) expression." (PMID 23844137, 2013). "Similarly, in the context of Trem-1−/− with angiotensin-II induced abdominal aortic aneurysm, inflammation and aortic wall degradation were markedly reduced, which was associated with decreased expression of Il1b, TNF-α, MMP2, and MMP9." (PMID 41226426, 2025).
abdominal aortic aneurysm (continued). "Furthermore, a link between genetic polymorphisms of MMP-9 and TIMP-1 and the unfavorable evolution of abdominal aortic aneurysm repair has been documented through a positive association with endoleaks incidence." (PMID 35563383, 2022). "It was reported that the prevalence of abdominal aortic aneurysm among the mice was reduced by up to three times due to RAGE knockout, and the underlying mechanism was explained by dose-dependent increases in MMP-9, along with increases in AGEs and signaling of the AGE/RAGE axis on macrophages." (PMID 35624800, 2022). "In addition, high expression of ITGAM is associated with unstable atherosclerotic plaques, and ITGAM knockout reduces macrophage infiltration, MMP9 expression, and elastin and collagen degradation in mouse abdominal aortic aneurysm models." (PMID 35656397, 2022). "It has also been reported that green tea phenol and tanshinone, a natural extract of Salvia miltiorrhiza, can effectively inhibit MMP-2 and MMP-9 activity to reduce the development of abdominal aortic aneurysms and that tanshinone has a better safety profile than doxycycline." (PMID 35463768, 2022). "Moreover, several authors have identified increased levels of VEGF, MMP-2, and MMP-9 in the blood of patients with abdominal aortic aneurysms." (PMID 34572455, 2021). "However, few studies have assessed serum MMP9 levels in both abdominal aortic aneurysm (AAA) and thoracic aortic aneurysm (TAA)." (PMID 30373522, 2018). "Based on these results, we confirmed that zinc treatment could suppress the inflammation and the expression of MMP-2 and MMP-9 in abdominal aortic aneurysm." (PMID 26918963, 2016). "MMP9 is also involved in abdominal aortic aneurysm formation." (PMID 23844137, 2013). "High serum levels of MMP-9 are found in moderate-diameter abdominal aortic aneurysms." (PMID 19250534, 2009). "Gene disruption of MMP-9 suppresses the development of experimental abdominal aortic aneurysms." (PMID 15482602, 2004). "Additionally, matrix metalloproteinase 9 (MMP9) is a crucial protein hydrolase involved in degrading various extracellular components of the aortic wall and is implicated in the pathogenesis of abdominal aortic aneurysms." (PMID 39044161, 2024). "In patients with abdominal aortic aneurysm, doxycycline treatment at a conventional dose, 200 mg/day, resulted in a mean plasma concentration of doxycycline at 4.6 μg/ml with a range of 1.3 to 14.4 μg/ml in humans, and there was a corresponding reduction in plasma MMP-9 levels." (PMID 15667660, 2005). "The overexpression of MMPs is reversible, as proven by a study conducted on patients with abdominal aortic aneurysm, in whom two different surgical approaches yielded a similar decrease in MMP-3 and MMP-9 levels." (PMID 39408865, 2024). "Throughout the progression of abdominal aortic aneurysm (AD), there is an upregulation in the degradation of the ECM and the expression of ECM enzymes, notably including MMP-9, MMP-2, and ADAMTs." (PMID 37836434, 2023). "In contrast, the inhibition of RAC1 can significantly inhibit the activation of NF-κB and lead to decreased expression of MMP-9, MCP-2 and CXCL5 in abdominal aortic aneurysm tissue." (PMID 36835806, 2023). "A previous study indicated that HO-1 knockout enhanced macrophage infiltration in abdominal aortic aneurysm, as well as increased the activity of MMP and upregulated the expression of MMP9." (PMID 35812724, 2022). "Both MMP9 and TLR4 seem to be overexpressed in patients with abdominal aortic aneurysms and seem to be together involved in the pathogenesis of aortic remodeling." (PMID 35563383, 2022). "A similar effect on the activation of both MMP–9 and MMP–2 proteins was found after application of quercetin in mice with abdominal aortic aneurysms." (PMID 32230721, 2020). "Abdominal aortic aneurysm (AAA)-MSCs were isolated from calcified and inflamed aortas of 12 patients with high serum levels of MMP-9 protein." (PMID 28446225, 2017).
abdominal aortic aneurysm (continued). "The results conclude that oral administration of sitagliptin can prevent abdominal aortic aneurysm formation in Ang II-infused apoE-/-mice, at least in part, by increasing of GLP-1 activity, decreasing MMP-2 and MMP-9 production from macrophage infiltration." (PMID 25876091, 2015). "The activation of MMP-9 and the TIMP-1 inactivation by HNE have important physiopathological role in cystic fibrosis lung disease, intracranial hemorrhage, abdominal aortic aneurysm and bone resorption." (PMID 21731773, 2011). "Glutamine protected against mouse abdominal aortic aneurysm through inhibiting M1 macrophage activation, secretion of IL-6 and TNF-α by macrophage, release of MMP-9 by RAW264.7 (macrophage) and MMP-2 by MOVAS (SMC), as well as apoptosis of vascular SMC by ROS and MMP." (PMID 38903916, 2024). "A study found that both MMP-2 knocked-out mice and MMP-9 knocked-out mice failed to develop abdominal aortic aneurysms (AAA) in a AAA mouse model, indicating that MMPs played a key role in aneurysmal diseases." (PMID 35045850, 2022). "Literature data indicated that MMP-9 clearance depends on the expression of low-density lipoprotein receptor-1 (LRP1) -bound protein, therefore, LPR1 is considered an important element in the pathogenesis of abdominal aortic aneurysm." (PMID 35745168, 2022). "In addition, a recent study noted that knockdown of PVT1 decreased levels of MMP-2 and MMP-9, augmented TIMP-1 expression, and suppressed serum levels of TNF-α, IL-1β, and IL-6 in VAMC and ApoE-/- mice of abdominal aortic aneurysm model." (PMID 34775377, 2021). "Indeed, MMP-9/TIMP-1 imbalance has been observed in sputum of patients with cystic fibrosis and in abdominal aortic aneurysm; where the high level of HNE promotes a large MMP-9 activation either directly or by the proteolysis of TIMP-1, its natural inhibitor." (PMID 21731773, 2011). "However, Ccl3−/− and Ccr5−/− (Chemokine receptors) mice exhibit exaggerated abdominal aortic aneurysm (AAA) with augmented macrophage infiltration and (matrix metalloproteinase) MMP‐9 expression, whilst CCL3 treatment reverses this phenomenon in both wild‐type and Ccl3−/− mice by the CCL3–CCR5 axis." (PMID 38709145, 2024). "In another study, even a reduction of MMP-9 concentration and activity has been reported in the plasma of LMWH-treated patients with abdominal aortic aneurysm, an effect which might be connected to the LMWH-dependent downregulation of IL-8 as shown in enoxaparin-treated epithelial cells." (PMID 30935029, 2019).
leukemia (54 papers, 2009 to 2025). A malignant (clonal) hematologic disorder, involving hematopoietic stem cells and characterized by the presence of primitive or atypical myeloid or lymphoid cells in the bone marrow and the blood. "For B-CLL, CCR7-enhanced expression of MMP-9 was associated with increased migration of leukemia cells to lymph nodes and for non-Hodgkin’s lymphoma to an increase in cancerous lesions." (PMID 35203305, 2022). "The top upregulated genes included gata2b (fc = 7.35), notch1b (fc = 2.07), gfi1ab (fc = 2.25) and mmp9 (fc = 2.36), which are required for maintenance and/or expansion of HSCs and multi-potent progenitors, or strongly implicated in leukaemia transformation." (PMID 36285442, 2022). "In contrast, a significantly reduced BCR-ABL1+ (GFP+) BP-1+ leukemia load (P = 0.003), as well as prolonged survival (P = 0.001) was observed in MMP-9-deficient mice with B-ALL." (PMID 31919471, 2020). "We transplanted total BM from wild type versus MMP-9-deficient recipient mice with established B-ALL into wild type secondary recipient mice to assess the self-renewal capacity of leukemia-initiating cells (LIC)." (PMID 31919471, 2020). "This revealed a significant reduction of leukemia load (P = 0.05), as well as significant prolongation of survival of secondary recipients transplanted with BM from MMP-9-deficient mice with B-ALL (P = 0.01)." (PMID 31919471, 2020). "To examine the clinical relevance of the MMPs identified here, we first determined whether MMP8 and MMP9 expression is associated with clinical outcome in leukemia patients." (PMID 38730491, 2024). "Especially MMP-9 is associated with extramedullary infiltration and leukemia invasiveness." (PMID 30634713, 2019). "In the present study we show that incubation of human leukaemia Mono Mac 6 cells in the presence of AA (20:4n-6) in serum-free medium is associated with increased secretion of MMP-9 to the growth medium in comparison with control cells incubated without added AA." (PMID 19331685, 2009). "The current study reported that MMP-9 was more expressed in leukemia relapse samples when compared to diagnosis samples and in healthy bone marrow compared to tumor tissue at diagnosis." (PMID 40427122, 2025). "We found that splenic leukemia cells of ROR1xTCL dTg mice have higher levels of MMP-9 than the similarly isolated splenic leukemia cells of TCL1 Tg mice." (PMID 40295829, 2025). "We found that culture of CLL cells in MSC-conditioned media (MSC-CM) enhanced leukemia-cell expression of MMP-9 in a time dependent manner." (PMID 40295829, 2025). "Using the leukemia cells from each of these transgenic mice we examined for MMP-9 in ROR1+ leukemia cells of ROR1xTCL1 dTg mice and ROR1Neg leukemia cells from otherwise syngeneic TCL1 Tg mice." (PMID 40295829, 2025). "Analysis of gene expression in these precursor cells identified pathways that were specifically upregulated, the most pronounced of which involved matrix metalloproteinases Mmp8 and Mmp9, during leukemia progression." (PMID 38730491, 2024). "Leukemia cells can also secrete MMP-9, which is known to facilitate progression and invasion of AML." (PMID 39125717, 2024). "Study has confirmed that during the pathogenesis of AML, MMP9 can partake in the escape of leukemia cells from the bone marrow via degrading the ECM, leading to the occurrence of extramedullary infiltration." (PMID 37200633, 2023). "MMP9- and CCL1-silenced DC-CIK cells alone or in combination also further facilitated the apoptosis of the cocultured leukemia cells with activated T cells, especially the combined treatment of MMP9 and CCL1 knockdown in DC-CIK cells." (PMID 37200633, 2023). "Some chalcones, such as isoliquiritigenin and butein, have been shown to decrease MMP9 and inhibit tumor cell invasion and metastasis in prostate and leukemia cells, respectively." (PMID 36687217, 2023).